CCL4 (C-C motif chemokine ligand 4)
Diseases named in the same sentence as CCL4 in open-access papers (continued):
Sharing a sentence is not in itself a finding about the gene and the disease.
hepatocellular carcinoma (17 papers, 2014 to 2025). A malignant tumor that arises from hepatocytes. "Gab1 knockdown in mouse hepatoma cells treated with CCL4 alone, or CCL4 plus HGF, showed a significant increase in cleaved caspase-3, along with decreased pERK1/2 and pSTAT3, as compared to control cells." (PMID 38935609, 2024). "We constructed DEN- and CCL4-induced spontaneous hepatocellular carcinoma models to investigate the role of HNF4A-AS1 in the initiation and progression of HCC, as well as its potential therapeutic value for HCC." (PMID 39430249, 2024). "In a previous study, WD + CCL4 resulted in stage 3 fibrosis at 12 weeks and hepatocellular carcinoma development at 24 weeks in mice." (PMID 36825196, 2023). "The reduction of hsa_circ_0098181 was confirmed in eight paired human HCC tissues, hepatoma cell lines, and CCL4/DEN-induced mouse HCC models by RT-qPCR." (PMID 35264957, 2022). "Protein expression was visualized by immunofluorescence, which shown that downregulating RDH5 in DEN and CCL4 induced-mouse hepatocellular carcinoma." (PMID 32788868, 2020). "To test this, we determined Gab1 expression following co-treatment with CCL4 and HGF using the mouse hepatoma cell line Hepa1-6 cells." (PMID 38935609, 2024). "Hepatoma cells showed elevation of p-Gab1, along with an increase in STAT3 and ERK activation, upon treatment with HGF (ligand of HGF receptor/c-Met) and CCL4." (PMID 38935609, 2024). "Ex vivo co-culture of hepatoma cells with neutrophils confirmed CCL4 upregulation, and patient-derived TANs secreted significantly higher levels of CCL4 than non-TANs." (PMID 41451221, 2025). "Furthermore, in cases of hepatocellular carcinoma (HCC), tumor cells harness the CCL4/CCL5 chemokine pathway, interacting with the CCR1/CCR5 receptors, thereby orchestrating the mobilization of γδ T cells either from the peripheral blood or peritumor region to the tumor region." (PMID 38077392, 2023).
colon carcinoma (16 papers, 2012 to 2025). "It was shown that the high level of ccl4 expression had induced tumor-associated macrophages (CD163+ cells) infiltration in colon cancer." (PMID 35463731, 2022). "The expression levels of both CCL4 and CCL2 were elevated in colon-cancer and lung adenocarcinoma tissues and were associated with shorter OS." (PMID 39996747, 2025). "Earlier studies showed high levels of MSC-secreted MIP-1b (CCL4) target CCR5 in colon cancer cells, promoting invasion and metastasis." (PMID 35511336, 2022). "According to a previous study, high CCL4 expression might stimulate the infiltration of tumor-specific macrophages in colon cancer." (PMID 34900664, 2021). "CCL4 is also a member of the family of beta chemokines that may function in ASPS in ways similar to those observed for CCL5 in colon cancer." (PMID 23226201, 2012). "Several studies have revealed that the up-regulation of CCL4 and CCL5 in gastric carcinoma, tongue squamous cell carcinoma (TSCC), and colon cancer resulted in the initiation of invasion steps." (PMID 38067251, 2023). "β-catenin also suppressed the transcription of T-cell recruiting chemokine, CCL4, from dendritic cells and thus reduced the infiltration of CD8+ T cells within the TME in colon cancer and melanoma." (PMID 34638390, 2021). "In addition to tumor-infiltrating immune cells, colon tumor cells might represent a CRC-intrinsic and β-catenin-regulated source of CCL4, as suggested in analogy to a similar phenomenon observed in the context of cutaneous melanoma disease." (PMID 36428508, 2022). "Recent reports described that a pharmacological inhibition of β-catenin could reactivate cancer immunity by increasing dendritic cells, upregulating CCL4, and promoting the intratumoral infiltration of CD8+ T cells in various tumor models, including colon cancer." (PMID 34638390, 2021).
HIV-1 infection (16 papers, 2007 to 2023). The type species of lentivirus and the etiologic agent of acquired immunodeficiency syndrome (AIDS). "CCL4, together with CCL5 (RANTES) and CCL3, is produced by CD8+ T cells and is a suppressive factor for HIV-1 infection; recombinant CCL4, CCL5 and CCL3 block HIV-1 infection of susceptible cells in vitro." (PMID 35967369, 2022). "Since it was reported that CC chemokines effectively inhibit HIV-1 infection of cells we compared the ability of chemokine CCL4 and peptides 15D and 15K to inhibit HIV-1 infection of monocyte-derived macrophages using p24 based infectivity assay." (PMID 21264298, 2011). "It is also based on single cell analyses of the CD4+ T cells undergoing a primary response where R5 HIV-1 infection and the synthesis of CCL4 were largely exclusive." (PMID 18941536, 2008). "Single cell analyses were carried out on day 7 of culture by intracellular staining and flow cytometry using fluorescent monoclonal antibodies to CCL4 and p24 as markers for β-chemokine and HIV-1 infection, respectively." (PMID 18941536, 2008). "Luminex analysis showed that CCL-3 and CCL-4 release was increased by R5 HIV-1 infection." (PMID 21767373, 2011). "Thus, CCL-3 and CCL-4 release by cultured decidua basalis mononuclear cells was enhanced by R5 HIV-1 infection." (PMID 21767373, 2011). "In addition, the primary alloantigen response provided a fortuitously optimal dynamic range of response for the bivariate analyses of CCL4 synthesis and HIV-1 infection monitored by intracellular CCL4 and p24 expression." (PMID 18941536, 2008). "It is more likely that CD8+ T cells in the peripheral blood and in other organs may be activated by PrEP to produce CCL4; nonetheless CCL4 produced distally from the male genital tract may diffuse to this and additional organs thus contributing to prevention of HIV-1 infection." (PMID 35967369, 2022). "The CCL4 rs1634507 polymorphism in promoter regions was not related to HIV-1 infection but could be significantly associated with Acquired Immune Deficiency Syndrome (AIDS) more-rapid disease progression." (PMID 28404909, 2017). "HIV-1 infection of human macrophages leads to the release of β-chemokines including CCL2, CCL3, CCL4, and CCL5." (PMID 38005838, 2023). "Although several studies have investigated the influence of HIV-1 infection and disease progression on circulating levels of CCL3, CCL4 and CCL5, results have been contradictory." (PMID 34987508, 2021). "We report that decidual mononuclear cells naturally produce large amounts of chemokines, and that R5 HIV-1 infection significantly enhances production of the β-chemokines CCL-3 and CCL-4." (PMID 21767373, 2011). "Study by Wen and colleagues also showed that expression of CCL3, CCL4 and CCL5 decreased in U937 promonocytes in response to HIV-1 infection." (PMID 17684570, 2007). "We speculate that the binding property of CCL4 and CCL3 to the CCR5 HIV-1 co-receptor may however result in a beneficial effect by preventing potential HIV-1 infection." (PMID 35967369, 2022). "CCL4 is a CC inflammatory chemokine, ligand for CCR5, a co-receptor for HIV-1 infection." (PMID 35967369, 2022). "In addition to CCL2, other CC chemokines, namely CCL3, CCL4 and CCL5, are constitutively released by MDM and their production can be further increased following HIV-1 infection of these cells." (PMID 25608886, 2015). "CCL3, CCL4, CCL5 and CXCL12 are important natural inhibitors of HIV-1 infection, and it possible that the activation of chemokine receptors may stimulate chemokine expression." (PMID 21264298, 2011). "The CC-chemokines CCL3, CCL4 and CCL5 have been found to block the entry of CCR5-tropic HIV into host cells and to suppress the viral replication in vitro, but the in vivo role of endogenous CC-chemokines in HIV-1 infection is still incompletely understood." (PMID 17684570, 2007).
HIV-1 infection (continued). "Here, we found that secretion of the β-chemokines CCL-3 and CCL-4 was significantly upregulated during R5 HIV-1 infection of decidual mononuclear cells, but not during X4 HIV-1 infection." (PMID 21767373, 2011).
influenza (16 papers, 2011 to 2025). An acute viral infection of the respiratory tract, occurring in isolated cases, in epidemics, or in pandemics; it is caused by serologically different strains of viruses (influenzaviruses) designated A, B, and C, has a 3-day incubation period, and usually lasts for 3 to 10 days. "A study of over 15 critically ill patients showed that CCL3 is augmented in lung aspirates of patients, and notably, at the serum level, there was an increment of CCL3 and CCL4 in comparison with mild cases of influenza infection." (PMID 35126379, 2021). "By day 7, expression of Ccl3, Cxcl9, Cd86, Il-6, Cd80, and Cxcl11 remained elevated in young adult lung in response to H1N1, while expression of Ccl5, Ccl4, and Cd40 remained elevated in response to either strain of influenza." (PMID 34829979, 2021). "Other chemokines elevated in influenza-infected Tpl2-/- mice, including CXCL10, CCL5, CCL3 and CCL4, are also overexpressed in human cases of lethal influenza infections and recognized for recruitment of inflammatory monocytes and neutrophils." (PMID 34691044, 2021). "Role of Hypercytokinemia/hyperchemokinemia in the Pathogenesis of Influenza pathway was found to be significantly upregulated in the severe group’s monocytes with DEGs of AREG, CCL3, CCL4, CXCL8, IL1B, and ISG15 (coverage = 7% and p < 0.001)." (PMID 37495649, 2023). "The study also revealed strengthened interactions of the Ccl5-Ccr5, Ccl4-Ccr5, and Ccl3-Ccr5 ligand/receptor pairs between CD8+ Trm and other memory subsets after influenza infection." (PMID 37415817, 2023). "During influenza, cytokines and chemokines such as type I and III interferons (IFNs), IL-6, CXCL8, CCL2, CCL3, CCL4, and CCL5 are produced at the site of infection (Wareing and others 2004)." (PMID 35674675, 2022). "CCL3 and CCL4, the other CCR5 ligands, are also expressed in response to experimental influenza infection in human volunteers." (PMID 35126379, 2021). "Chemokine receptor 5 (CCR5) and its cognate chemokines CCL3, CCL4 and CCL5 are rapidly induced upon influenza infection, contributing to leukocyte recruitment into the airways and a consequent effective antiviral response." (PMID 35126379, 2021). "Neutrophils isolated from influenza-infected mouse lungs were stimulated with CCR1, CCR5, CXCR2, and CXCR3 specific ligands CCL3, CCL4, IL-8, and CXCL11 (100 ng/mL), respectively, and incubated for 4 h." (PMID 31041196, 2019). "Influenza infection also induces the production of such cytokines as TNFa, IL-1, IL-6, and the mononuclear cell attractant chemokines: CCL-3, CCL-4, CCL-5, CXCL9, CXCL10, and CXCL11 in human monocytes, epithelial cells, and rat alveolar or murine macrophages." (PMID 30037133, 2018). "Neutrophils isolated from influenza-infected mouse lungs were stimulated with CCR1, CCR5, CXCR2, and CXCR3 specific ligands including CCL3, CCL4, IL-8, and CXCL11 (100 ng/mL) for 20 min, followed by incubation with a 1:10 ratio of Streptococcus pneumoniae (serotype 3) for 90 min." (PMID 31041196, 2019). "In addition to the known components of the hypercytokinemia response in influenza infection (IL6, IL29, CXCL10, CCL4) we have identified several other genes that our model can predict across species, which could be playing roles in initiating and/or sustaining this response." (PMID 22074594, 2011). "Although the chemokine receptor CCR5 does not actively participate in the infection process of influenza, after its activation by the chemokines CCL3/MIP-1α, CCL4/MIP-1β, and CCL5/RANTES, it becomes a key player in the inflammatory milieu that contributes to infection restraint." (PMID 35126379, 2021).
Stroke (16 papers, 2013 to 2025). Sudden impairment of blood flow to a part of the brain due to occlusion or rupture of an artery to the brain. "Patients with the highest quartile of CCL4 level showed a higher risk of stroke and cardiovascular events." (PMID 27553774, 2016). "Studies has been conducted in a cohort of hypertensive patients for an average follow-up period of 37.2 ± 19.9 months; the result found that elevated serum CCL4 levels is an independent predictor of stroke and cardiovascular events." (PMID 32194402, 2020). "Further, elevated serum CCL4 levels have been shown to be an independent predictor of stroke and cardiovascular events in an average follow-up period of 37.2 ± 19.9 months in a cohort of hypertensive patients." (PMID 27553774, 2016). "Additionally, the upregulation of chemokines and cytokines like Ccl7 and Ccl12 in microglia, Ccl4 and Cdkn1a in astrocytes, and Ccl4 in ependymal cells underscores the molecular mechanisms driving inflammation post-stroke." (PMID 39633897, 2024). "CCL4 was also identified upregulated in vulnerable AS plaques and was expressed by T cells in advanced atherosclerotic lesions in stroke patients, indicating that it might play a potential role in the development of AS." (PMID 31449494, 2019). "CCL4 was also upregulated in atherosclerotic plaques in stroke patients." (PMID 28710368, 2017). "Stroke resulted in upregulated expression of adhesion molecules (P‐selectin, E‐selectin, and ICAM‐1) and chemokines (CC‐chemokine ligand (CCL)‐2, CCL‐3, CCL‐4, CCL‐5, and chemokine C‐X‐C ligand 1 (CXCL‐1))." (PMID 37122157, 2023). "Impressively, TXL could inhibit the expression of stroke‐induced upregulated adhesion molecules (P‐selectin and ICAM‐1) and chemokines (CCL‐3, CCL‐4, CCL‐5, and CXCL1)." (PMID 37122157, 2023). "Impressively, TXL could inhibit the stroke‐enhanced expression of adhesion molecules (P‐selectin and ICAM‐1) and chemokines (CCL‐3, CCL‐4, CCL‐5, and CXCL1)." (PMID 37122157, 2023). "CCL4 is a ligand for CCR5, a chemokine receptor on macrophages, microglia, and T cells, and CCR5 was recently shown to be a promising target to ameliorate TBI and stroke suggesting that less of these cells may be beneficial to TBI." (PMID 34551293, 2021). "However, the expression of CCL2, CCL3, CCL4, CCL7, and CXCL2 was strongly increased after stroke, whereas CCL19, CCL20, and CXCL5 expression levels were not changed." (PMID 26640428, 2015).
colitis (15 papers, 2012 to 2025). Inflammation of the colon. "In C57BL/6 mice, the transition from day 7 to 12 was characterised by high diarrhoea scores, increased weight loss, increased macroscopical signs of colitis and peak colon levels of IL-1β, CCL2, CXCL2/3 and CCL4." (PMID 22279558, 2012). "However, only the expression of Cxcl2 and Ccl4 was markedly decreased in Npm1+/− ILC3s compared to WT ILC3s from mice with DSS-induced colitis." (PMID 39103576, 2024). "After 7 days of induced colitis, upregulation of the expression of 22 genes (Ccl2, Ccl3, Ccl4, Ccl5, Ccl6, Ccl7, Ccl12, Ccl17, Cxcl1, Cxcl2, Cxcl6, Cxcl9, Cxcl11, Ccr1, Ccr2, Ccr3, Ccr5, Ccr8, Cxcr2, Csf3, Osm, and Spp1) was observed in the CβG− group compared to the HβG- control group." (PMID 35163326, 2022). "Accordingly, we observed that the expression levels of genes encoding chemokines (Ccl3, Ccl4, and Ccl6), chemokine receptors (Ccr1, Ccr5, Cxcr2, Cxcl1, Cxcl2, and Cxcl13), and inflammatory factors (Mpo, Il-1β, and Il12) were increased in mice with DSS-induced colitis." (PMID 34795650, 2021). "Transcription levels of Cxcl9, Ccl3, Ccl4, and Ccl5, which facilitate effector CD8+ T-cell extravasation into tissues, were significantly lower in the tumors of colitis mice than in that of normal mice." (PMID 37605139, 2023). "Importantly, we found that growth factors (GFs) like VEGF, IGF, and PDGF as well as chemo-cytokines CCL2, CCL3, CCL4, CCL5, and CCL20 were significantly upregulated in colitis’s colonic tissues." (PMID 37691056, 2023). "After colitis induction, the KD protected intestinal barrier function, and reduced the production of RORγt+CD3− group 3 innate lymphoid cells (ILC3s) and related inflammatory cytokines (IL-17α, IL-18, IL-22, Ccl4)." (PMID 33888680, 2021). "These suggested that CCL4 might have mediated the effect of CD131 on chemotaxis of macrophages and T cells into the colon, as well as on inflammatory response in DSS-induced murine colitis." (PMID 40586774, 2025). "Therefore, it is possible that inhibiting the induction of CCL2 and CCL4 may reduce the migration of T cells in the colon and protect CD69 KO mice from severe colitis." (PMID 23785429, 2013). "In addition, the colitis induced a significant increase in the chemokines CCL4 and CCL5, although without significant differences between the Mcpt-4fl/fl and Mcpt-4ΔCre colitis mice." (PMID 40697820, 2025).
dengue (15 papers, 2012 to 2023). "Previous studies have reported elevated levels of IL-12 and CCL4 in patients with mild dengue fever." (PMID 31748599, 2019). "Further, parasitaemia levels displayed positive significant interactions with IL-6, CCL4 and IL-10 in the group of patients co-infected with malaria and dengue." (PMID 26271921, 2015). "Mast cells responded to antibody-enhanced dengue virus infection or polyinosiniċpolycytidylic acid treatment with the production of type I interferons and the rapid and potent production of chemokines including CCL4, CCL5 and CXCL10." (PMID 22479521, 2012). "It was found that for CBMCs, polyI:C and antibody-enhanced dengue virus infection were able to induce significant levels of CCL4, CCL5 and CXCL10." (PMID 22479521, 2012). "In particular, serum levels of CCL4 are increased in mild dengue and may be of good prognostic value." (PMID 30409217, 2018). "Studies show that elevated levels of IL-6, IL-10, IFN-γ, MIF, and CCL-4 could be used as potential predictors of severe dengue." (PMID 27903271, 2016). "It should be noted however that mast cell production of mediators such as CCL4 may also attract macrophages, which are primary targets of dengue virus infection." (PMID 22479521, 2012). "For malaria and virus coinfections, increased TNF, IFN-γ, IL-6, and CCL4 levels and decreased IL-4, IL-7, IL-12, TGF-β, and CCL3 levels were observed in malaria coinfections compared to dengue monoinfection." (PMID 36716305, 2023). "Among them, a vast panel of increased cytokines and chemokines in severe dengue, such as IFN-γ, GM-CSF, IL-10, CCL4/MIP-1β, IL-1β, CXCL8/IL-8 TNF-α, CXCL10/IP-10, CCL2/MCP-1, and IL-18." (PMID 35631030, 2022). "Serum levels of CCL3, CCL4 and CCL5 are altered and tissue levels of chemokine-producing cells are elevated in dengue patients." (PMID 30409217, 2018). "Circulating levels of CCL4 and CCL5 in dengue patients are positively correlated with good prognosis." (PMID 22479521, 2012). "Increased levels of TNF-α, IL-1β, IL-4, IL-6, IL-8, IL-13, IL-15, macrophage migration inhibitory factor (MIF), and chemokines CCL2, CCL4, CCL5, and CXCL10 (IP-10) among others, have been reported in patients with dengue hemorrhagic fever (DHF) when compared to dengue fever (DF)." (PMID 29986388, 2018). "Levels of the chemokine C-C ligands 2, 3 and 4 (CCL2, CCL3 and CCL4) have been correlated with severe dengue disease in humans in several studies, and mice lacking these chemokines have reduced lethality and milder disease during dengue infection." (PMID 28644404, 2017). "However, like HMC-1 cells, KU812 cells did produce CCL4, CCL5 and CXCL10 in response to antibody-enhanced dengue virus infection." (PMID 22479521, 2012). "While monocyte-derived dendritic cells can produce large amounts of CCL4 and CXCL10 in response to dengue virus, they are not resident in the dermis as mast cells are, and would not be activated immediately upon dengue virus infection." (PMID 22479521, 2012). "While the influence of CCL4 and CCL5 on the overall immune response to dengue virus infection is not well studied, clinically these chemokines are decreased in serum of dengue hemorrhagic fever patients, and therefore their levels may serve as good prognostic factors for disease outcome." (PMID 22479521, 2012).